CHRNA7 (cholinergic receptor nicotinic alpha 7 subunit)
Diseases named in the same sentence as CHRNA7 in open-access papers (continued):
Sharing a sentence is not in itself a finding about the gene and the disease.
autism (12 papers, 2011 to 2025). Persistent deficits in social interaction and communication and interaction as well as a markedly restricted repertoire of activity and interest as well as repetitive patterns of behavior. "Variations in CHRNA7 dosage have been linked to NDDs, as evidenced by its inclusion in the Simons Foundation Autism Research Initiative database as a strong candidate gene, with a score of 2.1." (PMID 40362210, 2025). "But, in humans copy number variations of the gene encoding for α7 nAChR subunit (CHRNA7) are associated with brain diseases such as epilepsy or autism." (PMID 34684720, 2021). "Therefore, genetic studies on the relationship of variants in candidate genes such as CHRNA7 and OTUD7A on 15q11-q13 with autism should be performed." (PMID 30108208, 2018). "A paternally inherited 15q13.2q13.3 microdeletion encompassing the gene CHRNA7 was detected in a boy with severe autism, absence of language and developmental delay." (PMID 33081247, 2020). "Additionally, we noted massive albeit bidirectional hippocampal changes in the autism-related transcripts of Grin2b, PTEN and SHANK3, predicting behavioral differences; but not in the inflammation-associated CHRNA7, indicating limited relevance for brain inflammation." (PMID 32503154, 2020).
depression (10 papers, 2011 to 2025). "We previously reported that FMT from Chrna7 KO mice with depression-like phenotypes caused depression-like behaviors, higher blood levels of IL-6, and downregulation of synaptic proteins in the PFC in ABX-treated mice." (PMID 35650202, 2022). "Lastly, the α7 neuronal nicotinic acetylcholine receptor subunit gene (CHRNA7) is a cholinergic receptor, which has been reported to be associated with a sensory deficit in common mental illness and neurochemical changes in depression-like behavior." (PMID 21494644, 2011). "Research has shown that SD significantly blocks systemic inflammation and depression-like behavior, alters the composition of gut microbiota in LPS-treated mice, and blocks depression-like behaviors in Chrna7-KO mice." (PMID 40835804, 2025). "For example, we previously reported that subdiaphragmatic vagotomy blocked the onset of a depression-like phenotype in mice after LPS administration, FMT from mice with depression-like phenotypes, or in Chrna7 knockout mice with depression-like phenotypes." (PMID 37402856, 2023). "Taken together, results from these assays suggest that Chrna7 deficient mice have no phenotypic differences in hyperactivity, anxiety, depression-like behaviors, or sensory-gating." (PMID 28045139, 2017). "FMT from Chrna7 KO mice induced depression in ABX mice by modulating the subphrenic vagus nerve, underscoring the potential involvement of the brain-gut microbiome axis in depression development via the vagus nerve." (PMID 38983862, 2024). "Some well-known depression candidate genes that do not have scores greater than 0.01 in the HuGE genes are included in our DEPgenes, such as DBH, CHRNA7, and GABRA3, which were all ranked in the top list of DEPgenes." (PMID 21494644, 2011).
bipolar disorder (7 papers, 2017 to 2025). A disorder of the brain that causes unusual shifts in mood, energy, activity levels and the ability to carry out day-to-day tasks. "The presence of heteromeric dupα7/α7 nAChRs, increased CHRFAM7A, and/or reduced CHRNA7 expression in the prefrontal cortex has been reported in patients with bipolar disorder and schizophrenia spectrum disorders." (PMID 37626860, 2023). "A reduced CHRNA7:CHRFAM7A ratio, due to increased CHRFAM7A and/or reduced CHRNA7 expression, has been reported in the prefrontal cortex of patients with bipolar disorder and schizophrenia." (PMID 35408823, 2022).
Intellectual disability (7 papers, 2012 to 2025). "In contrast, deletions involving the CHRNA7 gene, which encodes the alpha-7 nicotinic receptor highly expressed in the brain, are associated with phenotypic consequences such as intellectual disability, aggressive behavior, and ADHD, all typical of the 15q13.3 microdeletion syndrome phenotype." (PMID 41009966, 2025). "Case 2 presented a 418 kb duplication at 15q13.3 involving CHRNA7 and OTUD7A, a variant of uncertain significance correlated with intellectual disability, speech apraxia, and self-injurious behavior." (PMID 40943430, 2025).
autism spectrum disorder (6 papers, 2016 to 2025). A spectrum of developmental disorders that includes autism, and Asperger syndrome. "For autism spectrum disorder, DGCR2, ARVCF, GNB1L, COMT, ZDHHC8, CHRNA7, and NRXN1 are candidate genes with various associated developmental defects." (PMID 37486921, 2023).
lung carcinoma (6 papers, 2019 to 2025). "In fact, CHRNA7 (located at 15q13.3) gene duplication was found to increase lung cancer risk." (PMID 34771509, 2021). "Silencing CHRNA5 was found to exert opposite effects compared to silencing CHRNA7 on cell migration in lung cancer cells." (PMID 41201200, 2025). "The pathophysiological effects of nicotine and its derivatives are primarily mediated by nAChRs in target cells, especially in lung cancer, through sensitive subtypes of nAChRs, such as α7 (CHRNA7)." (PMID 39472448, 2024). "We investigated their prognostic significance in lung cancer patients and found CHRNA7 to be an independent prognostic factor." (PMID 36072788, 2022). "We have previously identified two gCNVs namely CNV-30450 in MAPKAPK2 and CNV-3956 in CHRNA7 as prognostic biomarkers for lung cancer survival based on candidate gene study design." (PMID 34178039, 2021). "Our previous studies demonstrated that nicotine could stimulate CHRNA7 expression in human bronchial epithelial cells (HBECs) and that HBECs could be used to study the pathogenesis of lung cancer through defined genetic manipulations." (PMID 34771509, 2021).
Anxiety (5 papers, 2017 to 2026). Intense feelings of nervousness, tension, or panic often arise in response to interpersonal stresses. "Examining the mRNA SLC1A2, SLC1A3, GRM5, GRIN2B, GRIN2C, GRIA1, CHRNA7, 5-HT2A, and 5-HT3A offers insight into the neurotransmission systems implicated in NP-related anxiety." (PMID 41515464, 2026). "Knockout of the gene CHRNA7 in129S7/SvEvBrd * C57BL/6J mouse cells, suggests a decrease in anxiety." (PMID 40560842, 2025).
dementia (4 papers, 2016 to 2025). Loss of intellectual abilities interfering with an individual's social and occupational functions. "The association between CHRNA7 polymorphisms and dementia was examined after adjustment for age, sex, APOE ε4 status, and education year." (PMID 27249957, 2016). "However, further studies are warranted to explain the involvement of this CHRNA7 variant in the risk of AD and other dementias." (PMID 40423221, 2025). "Genetic polymorphisms of CHRNA7 may be a potential marker of dementia, useful to identify a high risk or responder individuals." (PMID 33921376, 2021). "This case-control study examined the association between CHRNA7 polymorphisms and dementia risk." (PMID 27249957, 2016). "In fact, CHRNA7 SNPs (rs1514246, rs2337506, rs8027814) seem to possess protective factors in different forms of dementia including AD." (PMID 33921376, 2021). "No studies explored the gene-gene, gene-environment interactions between CHRNA7 polymorphism, apolipoprotein E (APOE) ε4 status and smoking on dementia risk." (PMID 27249957, 2016). "Meanwhile, nicotine is an agonist of α7nAChR, but no studies examined whether the association of CHRNA7 polymorphisms with dementia varied depending on the smoking status." (PMID 27249957, 2016). "Another class encountered in trials was represented by dementia therapeutic agents acting on neuronal acetylcholine receptor subunit alpha-4, neuronal acetylcholine receptor subunit beta-2, neuronal acetylcholine receptor subunit alpha-7 (gene names: CHRNA4, CHRNB2, CHRNA7, respectively)." (PMID 36467081, 2022).
developmental delay (4 papers, 2012 to 2024). "Although deletion of Chrna7 in mice does not cause overt structural abnormalities, recent studies indicate that haploinsufficiency in CHRNA7 may cause a range of neurodevelopmental phenotypes associated with the 15q13.3 syndrome, including developmental delay, mental retardation and seizure." (PMID 22852769, 2012). "Finally, another interesting gene that we have analysed and explored is the cholinergic receptor nicotinic alpha 7 (CHRNA7) gene, which is altered in six patients with ASD, ID and psychomotor developmental delay, two of whom have a parental origin." (PMID 38674362, 2024).
nicotine dependence (4 papers, 2018 to 2025). Physical and psychological dependence on nicotine. "Moreover, a study showed the association of CHRN genes (e.g., CHRNA7) with nicotine dependence differed in males and females." (PMID 31164900, 2019). "Given the context dependent effects of gene expression on smoking cessation and nicotine dependence, future studies should focus on genetic variation in the in CHRFAM7A and CHRNA7 genes in PWH seeking treatment for smoking." (PMID 39915881, 2025).
Obesity (4 papers, 2018 to 2023). Accumulation of substantial excess body fat. "The goal of this case report is to increase awareness concerning CHRNA7 15q13.3 microdeletion as part of the differential diagnosis of rapid-onset obesity associated with neuropsychiatric disorders in pediatrics." (PMID 33884253, 2021). "Accordingly, CHRNA7 expression and the CAP activation increase would contribute to the reduction of systemic inflammation in this population and could become a new therapeutic target in the treatment of obesity and T2DM." (PMID 36831101, 2023).
Angelman syndrome (3 papers, 2005 to 2022). A neurogenetic disorder characterized by severe intellectual deficit and distinct facial dysmorphic features. "These events distort the structure of CHRNA7 and are associated with Prader-Willi/Angelman syndrome and mental retardation." (PMID 29545933, 2018).
colorectal cancer (3 papers, 2019 to 2025). A primary or metastatic malignant neoplasm that affects the colon or rectum. "Further comparison of gene expression differences between right-sided and left-sided colorectal cancer tumor cells revealed that genes such as MTRNR2L8, CHRNA7, TFF1, and LYZ were more highly expressed in right-sided colorectal cancer." (PMID 41174721, 2025).
idiopathic generalized epilepsy (3 papers, 2012 to 2021). A generalised epilepsy that encompasses several common seizure phenotypes including childhood absence epilepsy, juvenile absence epilepsy, juvenile myoclonic epilepsy and epilepsy with generalized tonic-clonic seizures alone. "Deletion of CHRNA7 has been implicated in idiopathic generalised epilepsy (IGE) in individuals with 15q13.3 deletion syndrome." (PMID 22342432, 2012).
Sepsis (3 papers, 2018 to 2025). Sepsis is defined as life-threatening organ dysfunction caused by a dysregulated host response to infection. "CHRNA7 agonists have also shown protective effects in inflammatory conditions including arthritis, sepsis, encephalitis, and systemic inflammatory response syndrome." (PMID 40653990, 2025).
Stroke (3 papers, 2021 to 2025). Sudden impairment of blood flow to a part of the brain due to occlusion or rupture of an artery to the brain. "In the present study, we investigated the expression patterns of the α7nAChR encoding gene Chrna7 in the naïve mouse brain and evaluated the effect of the selective α7nAChR agonist AR-R17779 on stroke-induced brain injury." (PMID 34008839, 2021). "Overall, it would be interesting to learn, what role plays SLURP-1 in the NLRP3 inflammasome induced release of IL1β as this was recently shown to be present in MC and to be attenuated by classical Chrna7 activation in a stroke model." (PMID 33815383, 2021).
breast carcinoma (2 papers, 2022 to 2025). "In this study, we provide the first experimental evidence for CHRNA7 as a biochemical target in activating adaptive immune responses to reduce tumor burden and improve overall survival in immune competent murine breast cancer models." (PMID 40653990, 2025). "Based on the tumor permissive phenotype of CHRNA7KO mice, we tested the effect of a small molecule agonist of CHRNA7, AR-R17779, in several mouse models of breast cancer." (PMID 40653990, 2025). "Together these findings supported the importance of CHRNA7 as a novel therapeutic target expressed on dendritic cells based on its role in potentiating the adaptive immune response in mouse models of breast cancer." (PMID 40653990, 2025).
breast tumor (2 papers, 2023 to 2025). "E0771 breast tumor cells were implanted into CHRNA7KO mice to determine the role of CHRNA7, which is expressed in tumor-associated myeloid immune cells." (PMID 40653990, 2025). "Based on the impact that the knockout of CHRNA7 had on tumor progression and survival, as well as changes in myeloid immune cell gene expression and tumor infiltration, we chose to perform in vivo testing of AR-R17779 on breast tumor–bearing immune-competent mice." (PMID 40653990, 2025). "Increased CHRNA7 and ITGA5 expression correlates with poor prognosis in patients with various types of cancer including epidermoid carcinoma, while elevated CERK expression correlates with breast tumor recurrence." (PMID 37854069, 2023).
E. coli (2 papers, 2017 to 2020). "Chrna7 expression in the bone marrow cells from vagotomized E. coli pneumonia mice compared to sham E. coli pneumonia mice at 2 dpi was measured by RT-PCR analysis." (PMID 32867826, 2020). "coli pneumonia were decreased compared to those in Chrna7+/+ sham E. coli pneumonia at 2 dpi." (PMID 32867826, 2020). "Next, we tested whether the deletion of Chrna7 would affect the distribution of CD11b+ cells between the spleen and the lung during E. coli infection." (PMID 28529765, 2017).
pancreatic cancer (2 papers, 2018 to 2021). "Nevertheless, patients with higher CHRNA7 expression in resected pancreatic tumors had better survival compared to those with a lower level of expression (HR = 0.51, 95% CI = 0.26–0.99; 5-year survival 18% vs. 0%)." (PMID 29545933, 2018). "In order to function as an inborn anti-PDAC mechanism, circulating SLURP1 should bind CHRNA7 on pancreatic tumor cells and exert an anti-tumor effect." (PMID 29545933, 2018). "Moreover, SLURP-1 was found to antagonize biological functions attributed to Chrna7 in patients with pancreatic cancer or malignant melanoma." (PMID 33815383, 2021). "To substantiate our claim of SLURP1 having pathobiological relevance because of endocrine-like impact on CHRNA7-positive pancreatic lesions, we attempted to establish a connection between the level of SLURP1 in serum and the molecular landscape of pancreatic tumors." (PMID 29545933, 2018).
acute pancreatitis (1 paper, 2021). An acute inflammatory process that leads to necrosis of the pancreatic parenchyma. "By analyzing the KEGG pathway in this study, the authors speculate that CHRNA7 might be expressed in acute pancreatitis and play a key role in regulating inflammation." (PMID 34868345, 2021).
Allergy (1 paper, 2019). An allergy is an immune response or reaction to substances that are usually not harmful. "The up-regulated genes have been previously associated with asthma; hyper-reactivity and allergy (CCR2, HRH2, PTEN); lung development and apoptosis (CHRNA7, RTKN2); and immune function (GIMAP4, GIMAP7, KLRC3 and CD99)." (PMID 30971730, 2019).
anxiety disorder (1 paper, 2023). A category of psychiatric disorders which are characterized by anxious feelings or fear often accompanied by physical symptoms associated with anxiety. "They observed a four-fold increase in the rate of CHRNA7 gain among individuals (adolescents, emerging adults) with MDD and anxiety disorders." (PMID 37761973, 2023).
atopic dermatitis (1 paper, 2024). "We studied MCPs and Chrna7/SLURP1 and their interplay in a mouse model for noise induced stress (NiS) and atopic dermatitis-like allergic inflammation (AlD) and in cultured MC lacking Chrna7." (PMID 38891925, 2024).
childhood-onset schizophrenia (1 paper, 2022). "Deletions involving CHRNA7 are rare but are strongly associated with schizophrenia: these patients only have one copy of CHRNA7 and two copies of CHRFAM7A, leading to an altered CHRNA7/CHRFAM7A ratio, whereas 15q13.3 duplication has been linked to childhood-onset schizophrenia." (PMID 35408823, 2022).
chronic obstructive pulmonary disease (1 paper, 2022). A chronic and progressive lung disorder characterized by the loss of elasticity of the bronchial tree and the air sacs, destruction of the air sacs wall, thickening of the bronchial wall, and mucous accumulation in the bronchial tree. "Additionally, CHRNA7 gene duplication is associated with poor prognoses in lung cancer and chronic obstructive pulmonary disease (COPD)." (PMID 35892574, 2022).
chronic pancreatitis (1 paper, 2018). A chronic inflammatory process causing damage and fibrosis of the pancreatic parenchyma. "By qRT-PCR analysis, we found that CHRNA7 mRNA was expressed in all analyzed samples: normal (donor), inflammatory (chronic pancreatitis/CP), and cancerous (PDAC)." (PMID 29545933, 2018).
Crohn disease (1 paper, 2016). A gastrointestinal disorder characterized by chronic inflammation involving all layers of the intestinal wall, noncaseating granulomas affecting the intestinal wall and regional lymph nodes, and transmural fibrosis. "Biopsies of Crohn's disease (N = 31), however, showed only small changes in CHRFAM7A expression (p < 0.04) and no change in CHRNA7." (PMID 27051591, 2016).
endotoxemia (1 paper, 2025). "In models of injury and endotoxemia, the loss of CHRNA7 increases inflammatory responses by uncoupling the protective effects of innervation by the parasympathetic nervous system such as by the vagus nerve." (PMID 40653990, 2025). "Interestingly, however, T cells are known to synthesize acetylcholine, which stimulates CHRNA7 to complete a vagus nerve circuit that controls innate immune responses in endotoxemia." (PMID 40653990, 2025).
Fever (1 paper, 2021). Body temperature elevated above the normal range. "The detected activity of AChE in the fever group indicates that it was not degraded in the target tissue during behavioural fever, and this molecule could become available to interact with Chrna7, thus inhibiting the release of inflammatory factors." (PMID 34445566, 2021).
heart malformations (1 paper, 2023). "Whether the CHRNA7 gene dose is related to heart malformations requires further investigation." (PMID 37248535, 2023).
Hyperhidrosis (1 paper, 2020). Abnormal excessive perspiration (sweating) despite the lack of appropriate stimuli like hot and humid weather. "De Moura Júnior and colleagues reported higher expression of alpha-7 nicotinic receptor subunit (CHRNA7) in sympathetic ganglia of hyperhidrosis patients." (PMID 33378362, 2020).
inflammatory bowel disease (1 paper, 2022). A spectrum of small and large bowel inflammatory diseases of unknown etiology. "A similar conclusion was drawn by Baird and colleagues, who showed that CHRFAM7A expression was increased, and that CHRNA7 expression was decreased in Inflammatory Bowel Disease (IBD), thus suggesting that CHRFAM7A may be an unrecognized target for the development of therapeutics for IBD." (PMID 35408823, 2022).
ischemia (1 paper, 2021). A hypoperfusion of the BLOOD through an organ or tissue caused by a PATHOLOGIC CONSTRICTION or obstruction of its BLOOD VESSELS, or an absence of BLOOD CIRCULATION. "In the present study, we investigated the absolute expression of Chrna7 in brain regions known to be affected by ischemia–reperfusion injury induced by the tMCAO model, i.e. cortex, striatum, thalamus and hippocampus." (PMID 34008839, 2021).